STAT1 (signal transducer and activator of transcription 1)
Diseases named in the same sentence as STAT1 in open-access papers (continued):
Sharing a sentence is not in itself a finding about the gene and the disease.
lung adenocarcinoma (continued). "LINC00467 has been reported to be transcriptionally induced by STAT1 in lung adenocarcinoma cells; additionally, LINC00467 was up-regulated by TDG-mediated acetylation in non-small cell lung cancer." (PMID 33996559, 2021). "Upon searching published papers and the LncMap database, we identified that five TFs—DDX17, STAT1, PPARG, ETS1, and E2F6—were closely associated with adenocarcinoma of the lung and HCG23." (PMID 32322582, 2020). "In contrast, when murine cell lines CMT64/61 (C57BL/6 lung adenocarcinoma) and NIH/3T3 (murine fibroblast, deficient in some steps of IFN signaling) were infected with HMPV, we saw increased total and phosphorylated STAT1 and STAT2." (PMID 32635475, 2020). "Although STAT1 and STAT2 activate IRF1, the protein level of IRF1 was not correlated with that of STAT2 in all the tissues and had a significant correlation with that of STAT1 only in the normal tissue of lung adenocarcinoma." (PMID 30305853, 2018). "Here we directly evaluate the relative role of host STAT1 expression in immune cells and the PD-1/PD-L1 signaling axis in a murine model of lung adenocarcinoma." (PMID 30647851, 2018). "Since responders to in vivo blockade of PD-1 show a trend to upregulation of Stat1 expression in total lung cells, we next examined the role of STAT1 during lung adenocarcinoma development." (PMID 30647851, 2018). "In conclusion, we have revealed that IL-17 promotes IL-6, IL-8, and VEGF production in lung adenocarcinoma via STAT1 signalling." (PMID 27819281, 2016). "Here, we documented OSM inhibits the migration, invasion and proliferation of lung adenocarcinoma cell lines through a STAT1-dependent mechanism." (PMID 27486982, 2016). "We determined the role of IL-17 in STAT1 phosphorylation in human lung adenocarcinoma cells in vitro by qRT-PCR and WB." (PMID 27819281, 2016). "The human lung adenocarcinoma cell line, A549, was treated with IL-27 at time points from 0.25 to 72 hours and analyzed for activated or tyrosine phosphorylated STAT1 (P-STAT1) and STAT3 (P-STAT3) proteins by Western blot." (PMID 24274066, 2013). "Similarly, another study showed that overexpression of PSAT1 promotes the metastasis of lung adenocarcinoma via the inhibition of STAT1 as well as its downstream targets, IRF1 and IFNG." (PMID 40298450, 2025). "Furthermore, conditioned medium from irradiated and untreated CAFs was applied to A549 lung adenocarcinoma tumor cells to explore activation of STAT-1 and Smad2/3-dependent pathways via secretion of IFNs and TGF-β from CAFs respectively." (PMID 39308864, 2024). "In addition to the macrophage cell line, IR increased both the expression and phosphorylation of the STAT1 protein in A549 lung adenocarcinoma cells." (PMID 37048082, 2023). "Taken together, we demonstrate that Oct4 is a pro-survival factor by inducing Stat1 expression and that the Oct4/Stat1/Mcl-1 axis may be a potential therapeutic target for lung adenocarcinoma." (PMID 34685622, 2021). "In this study, we show that Stat1 plays an anti-apoptotic role in lung adenocarcinoma." (PMID 34685622, 2021). "Several initiated signaling pathways, including linc00467/miR-20b-5p/cyclin D1 pathway and STAT1-induced upregulation of linc00467 promoted lung adenocarcinoma progression through epigenetically suppressing dickkopf WNT signaling pathway inhibitor 1 to activate Wnt/β-catenin signaling." (PMID 34713767, 2021). "For instance, miR-944 inhibits lung adenocarcinoma tumorigenesis by suppressing STAT1." (PMID 34017248, 2021).
lung adenocarcinoma (continued). "Previous studies have revealed that both Oct4 and Stat1 are overexpressed in lung adenocarcinoma and might play a role in cell survival." (PMID 34685622, 2021). "We therefore examined whether Stat1 participates in IL-17-induced angiogenic factor production in lung adenocarcinoma." (PMID 27819281, 2016). "In conclusion, IL-17 may promote the production of the angiogenic inducers IL-6, IL-8 and VEGF via STAT1 signalling in lung adenocarcinoma." (PMID 27819281, 2016). "In addition to being a DNA synthesis inhibitor, fludarabine, acting as a selective Stat1 activation inhibitor, may be a potential therapeutic agent in combination therapy for lung adenocarcinoma by inhibiting the anti-apoptotic effects of Oct4." (PMID 34685622, 2021). "Therefore, in addition to its anti-apoptotic properties, Stat1 might contribute to the regulation of focal adhesion and the promotion of tumor migration in lung adenocarcinoma." (PMID 34685622, 2021). "Therefore, we used STAT1 knockout (KO) mice in our murine model of lung adenocarcinoma." (PMID 30647851, 2018). "Thus, we further explored the possibility that IL-17 might modulate STAT1 phosphorylation in human lung adenocarcinoma cells." (PMID 27819281, 2016). "Subsequently, we demonstrated the importance of MAPK signaling in the upregulation of PD‐L1 by growth factors and IFNγ in lung adenocarcinoma cell lines, which was mediated through CD274 mRNA stability and STAT1 activation." (PMID 30972766, 2019). "As expected, STAT1 knockdown partially inhibited IL-17-mediated IL-6, IL-8, and VEGF production in human lung adenocarcinoma cell lines in vitro, suggesting communication between STAT1 signalling and IL-17 in lung adenocarcinoma." (PMID 27819281, 2016). "We assess the effect of lung adenocarcinoma cells on TAM through detecting the expression of SHP2, p- STAT1, p-STAT3, p-STAT5, p-STAT6, IL-4, IL-10, Cathepsin-L, Cathepsin-S, Cathepsin-K and Arginase-1 in each group of THP1 cells cocultured with and without A549 cells by western blot." (PMID 38747738, 2024). "In addition, STAT1-induced upregulation of LINC00467 promotes the proliferation and migration of lung adenocarcinoma cells by epigenetically silencing DKK1 to activate Wnt/beta-catenin signaling pathway." (PMID 33996559, 2021). "Although CD274 transcription and MHC‐I‐related transcription are both regulated by STAT1 6, 35, MAPK inhibition, in contrast to JAK2 inhibition, does not affect MHC‐I expression, suggesting that MAPK activity primarily regulates CD274 mRNA stability in lung adenocarcinoma cells." (PMID 30972766, 2019). "However, the role of Jak-Stat family signalling, such as STAT1 signalling, in the IL-17-mediated regulation of IL-6, IL-8 and VEGF in lung adenocarcinoma remains unknown." (PMID 27819281, 2016). "Differential expression analysis between tumors with and without LOH confirmed an increase of PD-L1 and effector molecules such as granzymes-A, -B, and -H, as well as STAT1 and interferon (IFN)-γ, in lung adenocarcinoma with HLA LOH but not lung squamous cell carcinoma." (PMID 29107330, 2017).
diabetes (49 papers, 2007 to 2026). "Several studies have reported that STAT1 gain-of-function mutations induce the diabetes and multiple autoimmune diseases." (PMID 36561297, 2022). "This anecdotal evidence comes from a case report of a 15 year old boy with diabetes caused by a gain of function STAT1 mutation who was given Ruxolitinib (a JAK1/JAK2 inhibitor) to treat additional symptoms of this disorder including chronic candidiasis and autoimmune enteropathy." (PMID 37867531, 2023). "Thus, the results demonstrate that dapagliflozin not only improves hyperglycemia but also slows down the progression of diabetes-associated renal TIF by improving hyperglycemia-induced activation of the STAT1/TGF-β1 pathway." (PMID 31333586, 2019). "Actually, Stat1 was over-expressed in Timp3−/− diabetic kidney compared to the WT; moreover, abolishing Stat1 expression by RNA interference caused a complete rescue of FoxO1 expression, suggesting a possible role of STAT1 in linking Timp3 deficiency to FoxO1 regulation." (PMID 23401241, 2013). "In type 2 diabetes mellitus, IL-1β has previously been shown to regulate the recruitment of NF-κB and STAT1 transcription factors to the promoter region." (PMID 38891092, 2024). "Stat1 ablation in T1DM model mice (NOD mice) ameliorated diabetes and insulitis, suggesting that in addition to autoimmune mechanisms, GOF of STAT1 would directly contribute to the pathogenesis of diabetes by inducing apoptosis of the islet beta cells." (PMID 34887872, 2021). "Studies in disparate fields, including diabetes and UV irradiation of melanocytes, point towards several upstream signaling proteins, such as NF-κB, STAT1, and TLR-4." (PMID 33256011, 2020). "STAT1 deletion prevents cytokine-induced beta-cell death and diabetes induced by multiple low-dose treatments with streptozotocin in mice, and STAT1 can also regulate caspase expression." (PMID 32226409, 2020). "STAT1 was reported to play regulatory roles in the pathogenesis of diabetic complications, including diabetes with cardiovascular disease and diabetic nephropathy." (PMID 32438712, 2020). "In obesity-related type 2 diabetes mellitus, the E2 enzyme UbcH8 mediates STAT1 ISGylation, contributing to STAT1 activation and M1 macrophage polarisation in high-fat diet-induced obese mice, suggesting that targeting UbcH8 could be a therapeutic strategy." (PMID 40103488, 2025). "Furthermore, it has been shown that diabetes risk factors, such as hyperglycemia and hyperlipidemia can exacerbate diabetes symptoms by activating NF-κB and STAT1, which together reduce the number of B cells." (PMID 36561297, 2022). "Accordingly, ISG15 and PTP4A3 may interact with STAT1 to affect diabetes and IA, though more studies are needed." (PMID 36561297, 2022). "Collectively, these results indicate that PARP-1 depletion inhibited the osteogenic and atherogenic phenotype of macrophages by targeting Stat1 and may subsequently decrease atherosclerotic calcification in diabetes." (PMID 31924749, 2020). "Notably, Stat1 acts as a positive transcription factor by directly binding to the promoter of Runx2 and promoting atherosclerotic calcification in diabetes." (PMID 31924749, 2020). "In addition, PARP-1 inhibition downregulates Stat1/Runx2 transcriptional activity and alleviates atherosclerotic calcification in diabetes." (PMID 31924749, 2020). "Indeed, HDAC4 has been described to deacetylate STAT1 (signal transducer and activator of transcription 1), and thus suppress autophagy in diabetes models." (PMID 31861179, 2019). "Inhibition of Stat1 was involved in the antioxidant effect of SOCS1 in diabetes." (PMID 31337338, 2019). "As described in Sections 3.1.3 and 3.1.1.7, diabetes-related GLIS deficiency leads to preferential upregulation of the BimS isoform, and diabetes-related PTPN2 deficiency leads to increased activation of STAT-1 resulting in increased Bim transcription." (PMID 26405162, 2015).
diabetes (continued). "For instance, and based on this approach, we have already developed in vivo approaches to prevent experimental diabetes by blocking NF-κB and STAT-1 and identified several interesting targets for beta-cell imaging (Flamez D, Kutlu B, Goodman N and Eizirik DL, unpublished data)." (PMID 17302974, 2007). "As a further suggestion of a cooperative role between ROS and STAT1 activation, in NOX-deficient diabetic mice the reduced ROS levels were found to impair STAT1 activation, and to increase STAT6 activation, thereby promoting a M2 signature during diabetes progression." (PMID 34659222, 2021). "For hsa-miR-548k, main targets involved in diabetes-related pathways were identified, including TGFBR1, STAT1, NFKB1, MAPK1, and STAT5A." (PMID 40788916, 2025). "The diabetes model group's JAK2 and STAT1 mRNA expression levels were found to be considerably higher than those in the normal group (p < 0.05), and taurine treatment dramatically decreased these levels (p < 0.01)." (PMID 38560269, 2024). "PARP1 knockout can inhibit the signal transducer and activator of transcription 1 (STAT1)/RUNX2 axis and reduce AIC in diabetes." (PMID 37679327, 2023). "In diabetes and IA, ISG15 was upregulated as a co-interacting protein of STAT1, while PTP4A3 was downregulated as a co-interacting protein of STAT1." (PMID 36561297, 2022). "For example, STAT1 and L1CAM expressions were found to be jointly downregulated in diabetes-related skin disorders." (PMID 35003395, 2021). "The activation of STAT1, the phosphorylated form of STAT1 (p-STAT1), has been shown to be involved in tubular EMT and tubulointerstitial fibrosis (TIF) in animal models including diabetes." (PMID 33859563, 2021). "Consistent with previous study, diabetes led to the activation of STAT signalling pathway, as assessed by STAT1 and STAT3 tyrosine phosphorylation." (PMID 30955247, 2019). "In fact, high glucose levels induce angiotensin II-dependent activation of Jak2, Stat1, Stat3, and Stat5 and increase of TGF-β and fibronectin synthesis in rat mesangial cells of streptozotocin-induced diabetes." (PMID 26872211, 2016). "PARP1 knockout can inhibit the STAT1/RUNX2 axis and reduce AIC in diabetes." (PMID 37679327, 2023). "The regulation of CD36 by Stat1 may be important in other pathophysiological events involving CD36-dependent lipid uptake and inflammation, such as diabetes mellitus and the metabolic syndrome." (PMID 20011528, 2009). "In support of this, study of STAT1 in the pancreas of T1D donors reveals that its expression is strongly increased in insulin containing islets, with its levels being much more modest in islets without detectable insulin or in donors without diabetes." (PMID 37867531, 2023). "For example, it was reported that diabetes-prone NOD mice harboring beta-cells expressing a SOCS1 transgene had a markedly reduced incidence of diabetes, and the disease protection was correlated with enhanced suppression of STAT1 phosphorylation in SOCS1-expressing beta-cells." (PMID 30936880, 2019). "Studies have exhibited the existence of AP-1, NF-κB and (signal transducer and activator of transcription 1/3 (STAT1/ STAT3) regulatory sites in the promoter region of Nox5, and demonstrated that all of these sites are involved in the development of vascular complication in diabetes." (PMID 29682485, 2017).
prostate carcinoma (48 papers, 2008 to 2026). A carcinoma that arises from epithelial cells of the prostate gland. "Subsequent cellular phenotyping assays showed the role of STAT1 in prostate cancer progression and its association with CDKL3." (PMID 36899018, 2023). "Here the authors show that MSC-derived IL-28 induces prostate cancer cell apoptosis via IL-28Rα-STAT1 signalling, while acquired resistance to apoptosis is associated with a shift in IL-28Rα signalling via STAT1 to STAT3." (PMID 33526787, 2021). "In advanced prostate cancer, loss of STAT1 expression is a poor prognostic factor, particularly in a subgroup of patients with low nuclear androgen receptor expression." (PMID 28881828, 2017). "Indeed, in previous tissue-based studies the ratio of STAT1:STAT3 in tumor cells was highly prognostic in CRC, and in prostate cancer loss of STAT1 associated with increased recurrence." (PMID 38424636, 2024). "In addition, STAT1 abnormalities have been associated with increased resistance to docetaxel therapy against prostate cancer." (PMID 37511023, 2023). "MCP-1 was secreted from macrophages interacted with the CCR2 receptor on prostate cancer cells, thereby activating the JAK/STAT1 pathway, ultimately contributing to the progression of prostate cancer and its resistance to radiotherapy." (PMID 41856970, 2026). "In this study, we found that STAT1 enhanced the transcription of critical glycolytic enzymes, leading to an increase in lactate secretion from prostate cancer cells." (PMID 41856970, 2026). "In prostate cancer, SHP2 downregulates STAT1, as its loss enhances STAT1 phosphorylation and immune marker expression (HLA-ABC, PD-L1)." (PMID 41462587, 2025). "In prostate cancer, epigenetic changes of the STAT1 gene promoter and impairment of STAT1‐related signal transduction lead to impaired antigen presentation." (PMID 36524848, 2023). "Patients with localized prostate cancer who have high STAT1 expression have longer cancer-specific survival times, whereas patients with advanced prostate cancer who have low STAT1 expression experience early biochemical recurrence." (PMID 37511023, 2023). "Another gene affected by compound 6 was STAT1, which, in different tumor types (including prostate cancer), acts as a tumor suppressor and oncogene." (PMID 37511023, 2023). "Functionally, STAT1 is aberrantly overexpressed in prostate cancer and has a tumor-promoting effect similar to that of CDKL3." (PMID 36899018, 2023). "In contrast, CDK19 knockout had a stronger effect than CDK8 knockout on STAT1 S727 phosphorylation and a similar effect on gene expression in 22Rv1 prostate carcinoma cells that overexpress CDK19 relative to CDK8." (PMID 37378433, 2023). "The SOCS1/STAT1 pathway played a critical role in inhibiting the growth of prostate cancer by regulating macrophage polarization in the tumor microenvironment." (PMID 35600340, 2022). "Here, we report that bone-marrow derived MSCs produce IL-28 and that this provokes rapid apoptosis of bone metastatic prostate cancer cells via IL-28Rα-STAT1 signaling, which has known roles in apoptosis, and in anti-viral and immune responses." (PMID 33526787, 2021). "Here, we report MSC-derived interleukin-28 (IL-28) triggers prostate cancer cell apoptosis via IL-28 receptor alpha (IL-28Rα)-STAT1 signaling." (PMID 33526787, 2021). "In our study, SHP2 expression was very high in prostate cancer (PCa) cell lines, and the expression of phospho-signal transducer and activator of transcription 1 (p-STAT1) and STAT1 was very low." (PMID 28881828, 2017). "STAT1 promoter methylation in squamous cell carcinomas and prostate cancers has been proposed to be a mechanism whereby STAT1 transcription is repressed during transformation." (PMID 22264274, 2012).